ZMIZ2 (zinc finger MIZ-type containing 2)
Description:
Increases ligand-dependent transcriptional activity of AR and other nuclear hormone receptors.
Synonyms: KIAA1886; ZIMP7; hZIMP7; DKFZp761I2123; NET27; TRAFIP20
Tractability: PROTAC: UniProt records ubiquitination sites on it; ubiquitination databases record sites on it; its protein half-life has been measured.
Gene: Protein-coding gene on chromosome 7 (44,748,560 to 44,770,112, forward strand). Ensembl gene ENSG00000122515.
Subcellular location: Nucleus
Subcellular location (Human Protein Atlas): Nucleoplasm; Mitochondria
Gene Ontology:
Molecular function: protein binding; transcription coactivator activity; SUMO ligase activity; zinc ion binding
Biological process: positive regulation of transcription by RNA polymerase II; SMAD protein signal transduction; transforming growth factor beta receptor signaling pathway; regulation of transcription by RNA polymerase II
Cellular component: nuclear replication fork; nucleoplasm; nucleus; chromatin
Genetic constraint (gnomAD): Loss-of-function variants: 26 observed, 90.72 expected, observed/expected ratio (o/e) 0.29, 90% interval 0.21 to 0.4. The upper end of that interval is the gene's LOEUF score, 0.4, which puts it in group 1 of 6, group 1 being the genes least tolerant of losing a copy. Missense variants: 1,021 observed, 1,237.7 expected, observed/expected ratio (o/e) 0.82, 90% interval 0.78 to 0.87. Synonymous variants: 483 observed, 523.8 expected, observed/expected ratio (o/e) 0.92, 90% interval 0.86 to 0.99.
Homologues: Orthologues: chimpanzee ZMIZ2 (99% identical), macaque ZMIZ2 (99% identical), rat Zmiz2 (92% identical), rabbit ZMIZ2 (92% identical), guinea pig ZMIZ2 (91% identical), mouse Zmiz2 (91% identical), pig ZMIZ2 (89% identical), dog ZMIZ2 (86% identical), tropical clawed frog zmiz2 (70% identical), zebrafish zmiz2 (66% identical), Drosophila melanogaster tna (36% identical), Caenorhabditis elegans miz-1 (17% identical). Paralogues in human: ZMIZ1 (61% identical), PIAS1 (16% identical), PIAS3 (16% identical), PIAS2 (15% identical), PIAS4 (13% identical).